ENSG00000256950 (novel transcript)
Gene: Protein-coding gene on chromosome 12 (121,888,809 to 121,921,470, forward strand). Ensembl gene ENSG00000256950.
Genetic constraint (gnomAD): Missense variants: 87 observed, 92.09 expected, observed/expected ratio (o/e) 0.94, 90% interval 0.79 to 1.13. Synonymous variants: 39 observed, 33.69 expected, observed/expected ratio (o/e) 1.16, 90% interval 0.89 to 1.51.